CD4 (CD4 molecule)
Diseases named in the same sentence as CD4 in open-access papers (continued):
Sharing a sentence is not in itself a finding about the gene and the disease.
mesothelioma (44 papers, 2013 to 2026). A usually malignant and aggressive neoplasm of the mesothelium which is often associated with exposure to asbestos. "Our analysis also showed that immune cell infiltration mechanisms were associated with SMO and GLI1 expression, and that CD4+ T cells, neutrophils, and macrophages have an important impact on mesothelioma development and prognosis." (PMID 37139482, 2023). "Expression levels of both were associated with poor prognosis of mesothelioma and infiltration of immune cells such as CD4+T." (PMID 37139482, 2023). "In murine mesotheliomas, a robust association between percentage of CD4+CD25+Foxp3+ T cells and tumor size has been demonstrated." (PMID 33987190, 2021). "Interestingly, the number of T lymphocytes in mesothelioma tissue can influence prognosis; along this line, CD4+ T lymphocytes and CD8- T cells are associated with a better and poorer survival of PM patients, respectively." (PMID 38259475, 2023). "Based on co-expression patterns between ceRNA and immune cells, it was found that has-miR-582-5p, CASP9, dendritic cell rest, ANIX2, T cell CD8, and T cell CD4 memory rest may be associated with mesothelioma bone metastasis." (PMID 36439509, 2022). "Notably, based on the co-expression patterns between ceRNAs and Immune cells, we found that the hsa-miR-582-5p, CASP9, dendritic cells resting, ANIX2, T cells CD8, and T cells CD4 memory resting might be associated with the mesothelioma bone metastasis." (PMID 31681739, 2019). "Noteworthy observations included a significant infiltration of M1 macrophages and CD4 + T cells in mesothelioma, with genes SOAT1, MNDA, and ITGAM showing a positive correlation with the level of M1 macrophage infiltration." (PMID 40223054, 2025). "Compared to the control group, the proportions of CD4 + naive T cells and M1 macrophages were significantly increased in mesothelioma, suggesting their potential impact on the disease." (PMID 40223054, 2025). "Studies have shown that copper ion levels in mesothelioma affect the infiltration of CD4+ T cells, with an increase in CD4+ T cells when copper ion concentration significantly decreases, but the infiltration level of CD8+ T cells is not affected." (PMID 37427098, 2023). "Recent studies suggest that patients with mesothelioma undergoing immunotherapy (e.g., T cell therapies) or chemotherapy (e.g., gemcitabine) showed enhanced tumor immune cell infiltration (e.g., CD4 + T helper cells and CD8 + T cells) and prolonged survival." (PMID 35846349, 2022). "T cells from patients with mesothelioma stimulated by CD4 + lymphocytes in vitro showed a lower expression of interferon." (PMID 36498378, 2022). "Despite this abundance of CD4+ T cells, several studies have shown that the CD4+/CD8+ T cell ratio in MPEs is similar to matched peripheral blood samples in patients with mesothelioma." (PMID 33987104, 2021). "Increased pre- and post-chemotherapy frequencies of CD4+ T cells in MPE and tumors were associated with complete response and improved survival in chemotherapy treated mesothelioma patients." (PMID 33987104, 2021). "Second, PDT-based DC vaccination outperforms the capacity of anti-CTL4 antibodies to induce CD8+ and CD4+ T cell activation in mesothelioma-bearing mice." (PMID 32120810, 2020). "The few studies on effusions of mesothelioma patients mainly report on the presence of a limited array of immune cells, being CD4+ and CD8+ T cells and macrophages." (PMID 29163783, 2017). "CD4+ T cells were only slightly less effective than CD26int or CD26high, whereas 26neg T cells proved to be incapable of regressing mesothelioma." (PMID 29213079, 2017). "Further work to establish the targets of CD4+ T-cell recognition is needed to better understand the balance of effector and regulatory CD4+ T-cells in mesothelioma." (PMID 28817839, 2017).
mesothelioma (continued). "In vivo studies using a murine mesothelioma model showed that the lipid content of tumor-infiltrating CD4+CD8α- DCs, CD4-CD8α- DCs DCs and plasmacytoid DCs increased with tumor progression." (PMID 25886502, 2015). "Indeed, preclinical evidences in murine models of mesothelioma showed that chemotherapy in combination with immunotherapy increased the tumoral CD4+/CD8+ immune infiltrate and induced long term tumoral responses." (PMID 38259475, 2023). "In summary, these findings show that following autologous DC therapy in mesothelioma patients the frequencies of circulating CD4 T cells expressing HLA-DR, PD-1 or ICOS, as well as CD8 T cells expressing the co-inhibitory receptor LAG3 are significantly increased." (PMID 30245692, 2018). "This remained true also if only the 42 patients with epithelioid histology and who received chemotherapy were considered and suggest that CD4+ T-cells may also have a predictive value in mesothelioma." (PMID 28817839, 2017). "Furthermore, adoptive transfer into mesothelioma-bearing mice showed that CD4+CD26high T cells clear tumors significantly better than traditionally used CD8+ T cells." (PMID 29213079, 2017). "In summary, this study showed that mesothelioma tumors and their secreted factors promote DC lipid accumulation, reduce DC numbers, in particular cross-presenting CD8α+CD4- DCs, impair antigen processing and antigen presentation ability and skew DCs to produce tolerogenic cytokines." (PMID 25886502, 2015). "Furthermore, our in vivo mesothelioma studies showed that CD8α+CD4- DCs were reduced in dLN and spleen, implying that cross-presentation of antigens is impaired in lymphoid organs." (PMID 25886502, 2015). "However, our finding that PD-1 expression on circulating CD4+ T cells is prognostic for poor survival in patients with mesothelioma warrants validation in a larger cohort of patients and further investigation as a biomarker of response to immunotherapy in this patient group." (PMID 41574275, 2026). "Moreover, the administration of CD4+ M28z CAR‐T cells alone for mesothelioma is efficacious and contributes to tumor suppression and the administration of CD4+19z1+ T cells alone for B cell tumors could prolong the survival of tumor‐bearing mice." (PMID 37829505, 2023). "Furthermore, it was recently shown that human CD4 CD26high T cells engineered to express a mesothelin-chimeric antigen receptor (CAR) elicit stronger immunity against large established mesothelioma after adoptive transfer in NSG mice than other Th CD4 subsets engineered with the same CAR." (PMID 35572552, 2022). "PD-1 was the predominant IhR expressed by over 50% of MPE CD8+ and CD4+ T cells, similar to previous reports that studied MPE T cells and TILs in mesothelioma." (PMID 41574275, 2026). "Specifically, it has been shown in mesothelioma that dendritic cells fed with apoptotic mesothelioma cells can activate both CD8+ and CD4+ T cells resulting in tumor clearance, highlighting the existence of potent tumor antigens." (PMID 39921204, 2025). "In contrast to our findings, a previous study investigating tremelimumab monotherapy in patients with advanced, unresectable mesothelioma found a significant increase in blood CD3+ and CD4+ T-cells following treatment." (PMID 38349570, 2024). "The immune cell infiltrate of mesothelioma includes 20–40% T-lymphocytes, mainly CD8+ T-cells, but also CD4+ and CD4+ FoxP3+ T-cells." (PMID 38259475, 2023). "In mesothelioma treatment field, Wilms’ tumor suppressor gene (WT1) has been studied as cancer vaccine due to its ability to induce CD4 and CD8 WT1-specific reactions." (PMID 35785199, 2022). "To our knowledge, we are the first to describe the expression of TIM-3 and LAG-3 on CD4+ and CD8+ T cells and CD3-CD56+ NK cells in effusions of mesothelioma patients." (PMID 29163783, 2017).
mesothelioma (continued). "Studies highlight that engineered human CD4 CD26 high T cells, armed with a mesothelin-chimeric antigen receptor, elicit heightened immune responses against successful mesothelioma in NSG mice post-adoptive transfer, surpassing other helper CD4 subsets with the same CAR." (PMID 37892995, 2023). "In accordance with these findings, CD26hi/CD4+ T cells genetically engineered to express a CAR recognizing mesothelin, an antigen overexpressed in mesothelioma, displayed an outstanding capacity to traffic to, survive in, and regress solid tumors in NSG xenograft mesothelioma models." (PMID 34885056, 2021). "After chemotherapy, matched MPEs and tumor tissue from patients with mesothelioma displayed similar proportions of CD3+ T cells, CD4+ helper (CD25-) and CD4+ regulatory (CD25+CD127lo) T cells post-chemotherapy, but similarly, CD8+ T cells were greater in the MPE than matched tumor tissue." (PMID 33987104, 2021). "Interestingly, in contrast to evidence supporting an important role for CD4+ CAR T cells in humanized mouse models of mesothelioma or lymphoma, transfer of an equivalent number of murine CAR T cells prepared with a ~1:1 CD8+:CD4+ ratio was substantially less effective." (PMID 37291434, 2023). "Further, local effector CTL failure in mesothelioma is not mediated by CD4+CD25+FoxP3+ Treg cells, as while Tregs influence CTL responses when tumors are small, other immune suppressor cells (macrophages, in particular) play a major role in inhibiting effector CTL." (PMID 31998326, 2019). "In contrast, Salarolgio and colleagues reported that increased frequencies of CD4+PD-1+, CD4+TIM-3+, CD4+LAG-3+ T cells within tumour tissue, but not MPE correlated with poor survival in mesothelioma patients." (PMID 41574275, 2026). "In a mesothelioma mouse model, a tumor-selective oncolytic vaccinia virus expressing CXCL11 reportedly enhanced tumor infiltrating CTLs and NK cells, but not CD4+ T cells, and prolonged survival." (PMID 33777950, 2021). "Through antigen spreading these animals also developed tumor-specific cytotoxic CD8+ T cells, but neither CD4+ T cells nor antibodies, rejecting WT-AB1 mesothelioma." (PMID 26431275, 2015). "A significantly higher CD4+, but not CD8+, T cell infiltrate was seen in mesothelioma tumors undergoing copper lowering therapy." (PMID 24013775, 2013). "However, while combination treatment significantly improved survival and cure rate in a CD4+ and CD8+ T cell dependent manner in AB1-HA murine mesothelioma, this effect was model-selective, and could not be replicated using other cell lines." (PMID 38350880, 2024).
autoimmune uveitis (43 papers, 2007 to 2026). An autoimmune form of uveitis (disease). "Furthermore, the higher concentration of formin like 1 in CD4+ T cells of ERU cases was also linked to the activation of those cells in the quiescent stage of equine recurrent autoimmune uveitis." (PMID 34385998, 2021). "In contrast, CD4+CD25+ Treg are implicated in the protective mechanism of DNA vaccination against experimental autoimmune uveitis which suggests that the role of Treg during DNA vaccination differs between the different disease models and/or immunization regimens." (PMID 18997868, 2008). "Activation of retina-specific CD4+ T cells capable of breaking through the blood-retinal barrier (BRB) was significantly associated with the onset and progression of autoimmune uveitis (AU)." (PMID 41632039, 2026). "The pathogenesis of autoimmune uveitis is driven by autoreactive CD4+ T cells from the periphery, which cross an impaired BRB, infiltrate the immune-privileged inner eye, and target retinal autoantigens, causing detrimental inflammation and destruction." (PMID 40001591, 2025). "Modulating the oxidation of LCFAs and SCFAs in CD4+ T cells also holds promise for the treatment of autoimmune uveitis and ERU by regulating the Th17/Treg balance, potentially enhancing the immunoregulatory effects of Tregs." (PMID 39519064, 2024). "have demonstrated that dysfunction or dysregulation of CD4+CD25+ Treg cells are essential in the recurrence or progression of autoimmune uveitis in rats, and CD4+CD25+ Treg cells are involved in the alleviation of intraocular inflammation." (PMID 39076973, 2024). "We characterized the whole landscape of the lactylated proteins of CD4+ T cells in autoimmune uveitis." (PMID 37851814, 2023). "Previous experimental and clinical studies demonstrated the important role of dysregulated CD4+ T cell differentiation in autoimmune uveitis development." (PMID 37851814, 2023). "Overall, we propose an important function of lactylation in CD4+ T cell differentiation and provide insights into the pathogenesis of autoimmune uveitis." (PMID 37851814, 2023). "Future studies are required to use a larger cohort to validate the distinctive roles of CD4+ or CD8+ T cells in autoimmune uveitis in VKHD and BD." (PMID 37720629, 2023). "It is known that in experimental autoimmune uveitis, T-lymphocytes, especially CD4 + T-lymphocytes, play a central role in its immunopathogenic mechanisms." (PMID 37089809, 2023). "Inflammation triggers the activation of CD4+T cells and the breakdown of blood–retinal barrier, thus contributing to the pathology of experimental autoimmune uveitis (EAU)." (PMID 35401507, 2022). "To our knowledge, we are the first to describe this altered metabolic phenotype in CD4+ T cells of cases affected by spontaneous autoimmune uveitis." (PMID 34385998, 2021). "Functional studies are necessary to further research this interesting topic in the future, like it was recently done in a study on murine interferon regulatory factor-4 (IRF4) depleted CD4+ T cells of an experimental autoimmune uveitis model (EAU)." (PMID 34385998, 2021). "Antigen-responsive CD4+ T cells from EAU mice transferred into naïve mice initiate autoimmune uveitis, and different effector T cells can induce experimental models with different pathological phenotypes." (PMID 34733288, 2021). "This is consistent with data from animal models of autoimmune uveitis that find that T cell infiltration with CD4+ and CD8+ cells is an early feature in the development of disease." (PMID 31877281, 2020). "Autoimmune uveitis is mediated by CD4+Th cells which recognized peptide presented on MHC class II molecules." (PMID 33193382, 2020). "EAU resembles the key immunological characteristics of autoimmune uveitis in humans, as both are CD4+ T cell–mediated." (PMID 33117376, 2020).
autoimmune uveitis (continued). "We next asked if the Treg subset that was previously identified in mice that suppresses autoimmune uveitis as PD-1+FoxP3+CD25+CD4+ 15 can be induced through stimulation of the melanocortin-adenosinergic pathway." (PMID 31729418, 2019). "Since monocytes influence the T-cell response and CD4+ T cells are known modulators of autoimmune uveitis in mice and humans, we analyzed their T-cell cytokine pattern next." (PMID 30105034, 2018). "In this study, our overall goal is to test targeting CdK2 as a novel strategy to modulate CD4+ T cell response and thus treat autoimmune uveitis." (PMID 24260551, 2013). "Autoimmune uveitis is driven by activated CD4+ T cells that differentiate into effector T helper cells (Th1, Th2, and Th17) which release proinflammatory cytokines that damage the retina." (PMID 23785488, 2013). "Autoimmune uveitis is a T cell-mediated disease driven by CD4+T cells with aTh1 phenotype and can be inducedsuccessfully by adoptive transfer of antigen-specific CD4+T cellsand T cell lines." (PMID 18317528, 2007). "However, this was relatively rare in comparison to leukocyte-mediated strong expression of MHC-II colocalizing with CD45+CD4+ cells, the major antigen presenting cells during experimental autoimmune uveitis." (PMID 39198470, 2024). "Specifically, in an IRBP-TCR Tg model of spontaneous autoimmune uveitis (EAU), in which there are ~ 30% IRBP-TCR specific CD4 T cells, it has been proposed that IOI is caused by antigen-specific T cells activated in the bowel by IRBP/commensal-antigen cross-reactive peptides." (PMID 36690619, 2023). "Here, a connection between knockout of IRF4 and lower mitochondrial respiration in basal state in CD4+ T cells and suppressed autoimmune uveitis could be shown." (PMID 34385998, 2021). "Indeed, our current study revealed that DH exhibits potent anti-proliferative effects on autoreactive CD4+ T cells and ameliorates the development of experimental autoimmune uveitis." (PMID 33117376, 2020). "Our study demonstrates that zebularine restrains IFN-γ and IL-17 expression and promotes Foxp3 expression in CD4+ T cells and may serve as a candidate therapeutic agent for autoimmune uveitis." (PMID 31475011, 2019). "Additionally, these MHC class IIloLy6G-Ly6ChiCD11b+ cells suppressed CD4+ cell proliferation, inhibited Th1 and Th17 cell differentiation and induced CD4+ cell apoptosis when used for the treatment experimental autoimmune uveitis in a mouse model." (PMID 30254638, 2018). "In addition to the roles in the granulocytes, Mir223 has been known to be functional particularly in CD4+Th17 cells, which exacerbated the experimental autoimmune uveitis (EAU) by promoting autoreactive Th17 cell responses by inhibiting transcription factor FOXO3 expression." (PMID 33574820, 2020). "In the context of autoimmune uveitis, the nature of the APC responsible for initiating and sustaining the CD4+ T cell response is still a subject of debate." (PMID 40001591, 2025). "The results strongly suggest the distinctive roles of CD4+ and CD8+ T cells in the pathogenesis of autoimmune uveitis between VKHD and BD." (PMID 37720629, 2023). "The differential contribution of CD4+ and CD8+ T cells in autoimmune uveitis in VKHD and BD, respectively, is also supported by the analyses of T cell clonality." (PMID 37720629, 2023). "Studies in experimental autoimmune uveitis (EAU), animal models for autoimmune panuveitis or posterior uveitis in the human have learned that autoreactive CD4+ T cells play an important role in ocular inflammation." (PMID 34733288, 2021). "Autoimmune uveitis is characterized by non-infectious ocular inflammations with recurring and remitting episodes, driven by CD4+ T cells crossing the blood-retinal barrier and contributing to inflammation." (PMID 39519064, 2024).
autoimmune uveitis (continued). "Although it is possible that expanded CD4+ or CD8+ T cell clones in autoimmune uveitis recognise microbial epitopes not included in the database, we favour the hypothesis that these expanded T cell clones are driven by the recognition of ocular autoantigens." (PMID 37720629, 2023). "Since the experimental autoimmune uveitis model of VKH became widely accepted in the 1990s, several animal experiments have indicated that with leukocyte infiltration of the retina, CD4+ T cells, Th1 cells and Th17 cells may be activated to trigger autoimmune responses and ocular inflammation." (PMID 35958546, 2022).